CASP1 (caspase 1)
Diseases named in the same sentence as CASP1 in open-access papers (continued):
Sharing a sentence is not in itself a finding about the gene and the disease.
inflammatory bowel disease (8 papers, 2013 to 2024). A spectrum of small and large bowel inflammatory diseases of unknown etiology. "This receptor has been largely associated with inflammatory diseases, including inflammatory bowel diseases, and it can signal through caspase-1 to cause the production of pro-inflammatory IL-1β and IL-18, as well as TNF-α and nitric oxide, from inflammatory cells." (PMID 29167643, 2017). "Caspase-1 is involved in the pathogenesis of inflammatory diseases, including inflammatory bowel disease, neurodegenerative diseases, and endotoxic shock." (PMID 29184853, 2017). "In conclusion, we systematically summarized the landscape of pyroptosis in inflammatory bowel disease and identified AIM2, CASP1, CASP5, GSDMD, and NLRP3 as hub genes." (PMID 37740137, 2023).
memory impairment (8 papers, 2020 to 2025). "Here, we reported that pharmacological intervention immediately after HIBD or genetic ablation of caspase-1 improved HI-induced myodynamia, motor coordination, learning, and memory impairment in animal models." (PMID 37620837, 2023). "For instance, the activation of NLRC4 inflammasome interacts with CASP1, IL-1β, and p-Tau to contribute to neuroinflammation and memory impairment." (PMID 35783533, 2022). "It has been demonstrated that cleaved caspase-1 expression is strongly higher in human AD brains, and NLRP3 or caspase-1 gene knockout AD mice have less memory impairment and enhanced Aβclearance." (PMID 40357234, 2025). "The hippocampus-dependent memory impairment induced by the cecal perforation (CLP) was accompanied by increased levels of NLRP3, caspase-1, and proinflammatory cytokines." (PMID 35571246, 2022). "Strawberry and selenium, when administered individually, significantly attenuated memory impairment, oxidative stress, neuroinflammation, and apoptosis, as evidenced by marked normalization of Nrf2/HO-1, TAC, SOD, MDA, TLR4/NF-κB/TNF-α, NLRP3/CASP-1/IL-1β, and BAX/Bcl-2 signaling." (PMID 41471381, 2025). "Additionally, autophagic inhibitor 3-MA treatment worsened ethanol-induced memory impairment, while autophagy activation with rapamycin suppressed IL-1β and IL-18 genes transcription and NLPR3, pro-Caspase-1 and Caspase-1 proteins expression in ethanol-induced microglia and mice." (PMID 37548945, 2024).
pancreatitis (8 papers, 2022 to 2025). Inflammation of the pancreas. "Baicalin alleviates pyroptosis and inflammatory response in hyperlipidemic pancreatitis by inhibiting the NLRP3/Caspase-1 pathway." (PMID 40620677, 2025). "Research has shown that inhibiting the NLRP3/Caspase-1 signaling pathway can alleviate pyroptosis and inflammatory response in hyperlipidemic pancreatitis models." (PMID 38125797, 2023). "Therefore, targeting of TLR4 upstream of caspase-1 could at least partially inhibit cleaving and activation of caspase-1, which would result in more beneficial outcomes to those suffering from pancreatitis." (PMID 38585277, 2024). "Therefore, HDL may alleviate pyroptosis and inflammatory response in hyperlipidemic pancreatitis models by inhibiting the NLRP3/Caspase-1 signaling pathway." (PMID 38125797, 2023). "It has been reported that deletion of caspase-1, ASC or NLRP3 significantly reduced edema and inflammation of AP; previous studies also indicated that knockdown of caspase-1 significantly reduced the degree of death and inflammation of pancreatitis follicle cells." (PMID 37370098, 2023). "Therefore, after GQD intervention, the production of NLRP3 can be inhibited, thereby reducing the synthesis of Caspase-1 and GSDMD, lowering the release of inflammatory factors such as IL-1β and IL-18, and increasing IL-10 levels, thereby preventing the progression of post ERCP pancreatitis." (PMID 40620677, 2025).
preeclampsia (8 papers, 2020 to 2025). Preeclampsia is a hypertensive disorder of pregnancy that is characterized by new-onset hypertension with proteinuria presenting after 20 weeks of gestation, and depending on mild or severe forms may initially present with severe headache, visual disturbances, and hyperreflexia. "The preeclampsia group had the least placental damage (placental expression: caspase-3 [9.88±3.25], caspase-1 [4.21±3.16], and TNF-alpha [7.42±4.28])." (PMID 37362630, 2023). "Activation of Caspase 1 in the inflammasome pathway can also result in pyroptosis by cleavage of Gasdermin D, as also observed in the placentae of patients with preeclampsia." (PMID 37047793, 2023). "Numerous studies have demonstrated an upregulation of NLRP1 and Caspase-1 in the placenta of preeclampsia, suggesting that the NLRP1 inflammasome mediates inflammatory responses and contributes to placental injury in preeclampsia." (PMID 40242759, 2025). "This pathway is also involved in the placental changes seen in preeclampsia, miscarriage, and gestational diabetes, and it involves activation of the intracellular innate immunity receptor NLRP3, with subsequent production of Caspase 1, IL-1β, and IL-18." (PMID 37047793, 2023). "However, preeclamptic placentas secrete higher levels of IL1β into the maternal circulation and key components of the inflammasome including ASC, cleaved caspase-1, GSDMDNT, and HMGB1 are increased in the placenta from women with preeclampsia." (PMID 37292200, 2023).
tauopathies (8 papers, 2020 to 2026). "Our current study evaluated the impact of Caspase-1 common variant rs554344 on the pathological processes of brain amyloidosis, tauopathy, and neurodegeneration." (PMID 35172755, 2022). "In general, patients affected by tauopathies showed elevated levels of cleaved caspase-1 and ASC and mature IL-1β in the cortex." (PMID 33362788, 2020). "Having demonstrated that pyroptosis occurs as a consequence of sevoflurane-mediated inflammation, we decided to explore whether caspase-1, the activation of which induces pyroptosis, affects the pathogenesis of tauopathies." (PMID 35127716, 2021). "Thus, our findings suggest that caspase-1 plays a role in sevoflurane-induced pyroptosis and establishes a link between pyroptosis and tauopathies." (PMID 35127716, 2021). "Also, Tau22 mice, another model of AD and other tauopathies, had increased levels of cleaved caspase-1 and ASC in their brain at the age of 11 months compared to their 3-month-old counterparts." (PMID 33362788, 2020). "While the precise role of caspase-1 in AD neuropathology remains unclear, compelling evidence suggests that targeting caspase-1 could be a viable therapeutic approach for addressing AD and possibly other tauopathies, alone or combination with drugs targeting Nlrp1 and caspase-6." (PMID 38419122, 2024). "Despite the distribution of the Caspase-1 rs554344 frequency between NC and MCI being similar, our current results support the role of Caspase-1 rs554344 in AD tauopathy." (PMID 35172755, 2022). "FX5 ameliorated synaptic impairment through GR/BDNF/TrkB/CREB pathway, protected against neuronal apoptosis by repressing GR/PI3K/AKT/GSK3β pathway-mediated tauopathy and subsequent ER stress and repressed inflammation through GR/NF-κB/NLRP3/ASC/Caspase-1 pathway." (PMID 35260821, 2022). "Overall, our data indicate that extracellular tau protein stimulates microglia to phagocytose live neurons via Toll-like 4 receptor–NLRP3 inflammasome–caspase-1 axis and NADPH oxidase, each of which may serve as a potential molecular target for pharmacological treatment of tauopathies." (PMID 37402829, 2023). "Caspase-1 knockout reduced the viability of BV2 microglia, but not LDH release, and increased IL-1β levels, which not only affected the function of sevoflurane but also indicated that microglia-derived IL-1β causes tauopathy deterioration, as observed with other tau kinases." (PMID 35127716, 2021).
triple-negative breast carcinoma (8 papers, 2022 to 2025). An invasive breast carcinoma which is negative for expression of estrogen receptor (ER), progesterone receptor (PR), and human epidermal growth factor receptor 2 (HER2). "Nigericin causes triple-negative breast cancer cell death by inducing concurrent caspase-1/GSDMD-mediated pyroptosis and promoting the infiltration and activation of T cells, making it a promising antitumour agent, especially when combined with anti-PD-1 antibody treatment." (PMID 39616223, 2024). "The in vitro and in vivo results demonstrated that IC@PCH NP-mediated photothermal-chemotherapy treatment led to pyroptosis via the NLRP3/caspase-1 classical pathway, which had a significant therapeutic effect on triple-negative breast cancer." (PMID 40376201, 2025). "Recently published studies have shown that Cisplatin induces scorch death through activating the MEG3/NLRP3/caspase-1/GSDMD pathway in triple-negative breast cancer." (PMID 35938142, 2022). "In triple-negative breast cancer, cisplatin activated MEG3/NLRP3/CASP-1 pathway to induce cell pyroptosis, which suggested that MEG3 was involved in the pyroptosis pathway of cisplatin therapy." (PMID 36281290, 2022).
acute coronary syndrome (7 papers, 2020 to 2026). Signs and symptoms related to acute ischemia of the myocardium secondary to coronary artery disease. "Next, we analyzed the expression pattern of TFG and pyroptosis-associated genes caspase-1 and NLRP3 using GEO datasets (GSE10220), including 48 macrophage and 48 monocyte samples from 86 patients with symptoms of the acute coronary syndrome." (PMID 35091545, 2022). "In patients with an acute coronary syndrome, colchicine limited IL-1β secretion and intracellular content, while also diminishing pro-caspase-1 mRNA and secreted caspase-1 protein levels." (PMID 36555579, 2022). "In acute coronary syndrome (ACS), the overexpression or inhibition of IRF-1 effectively modulated caspase-1 activation, macrophage lysis and GSDMD expression, suggesting that IRF-1 potently activates ox-LDL-induced macrophage pyroptosis." (PMID 36544106, 2022). "In studies of acute coronary syndrome (ACS), colchicine has been shown to prevent NLPR3 inflammasome-induced caspase-1 activation, leading to decreased levels of interleukin IL-1b, IL-18, and IL-6 and CRP and a reduction in mortality from major cardiovascular events." (PMID 33133323, 2020).
acute myeloid leukemia (7 papers, 2020 to 2024). Acute myeloid leukemia (AML) is a group of neoplasms arising from precursor cells committed to the myeloid cell-line differentiation. "In immune cells and AML (acute myeloid leukemia) cells, the anti-cancer drug talabostat induces CARD8 activation and causes caspase-1-dependent pyroptosis." (PMID 32640751, 2020). "DPP8/9 inhibitor induces pyroptosis through CARD8 activation of pro-caspase-1 demonstrated in human acute myeloid leukemia (AML) cell lines and primary AML samples." (PMID 36172198, 2022). "Small-molecule inhibitors of the serine dipeptidases DPP8 and DPP9 (DPP8/9) activated CARD8 and caspase-1 to trigger pyroptosis in the majority of human acute myeloid leukemia (AML), indicating the protein CARD8 could be a novel therapeutic target for AML." (PMID 34298833, 2021).
atopic dermatitis (7 papers, 2013 to 2025). "IL-18, traditionally thought of as a Th1-promoting cytokine, has been implicated in the development of atopic dermatitis; transgenic mice expressing either human caspase-1 or IL-18 in keratinocytes develop spontaneous atopic dermatitis-like lesions with elevated mast cell activity." (PMID 24409181, 2013). "The exotoxin α-toxin from Staphylococcus aureus (S. aureus) induced IL-1β secretion mediated by caspase-1 activation in monocytes from healthy controls, and IL-1β secretion by α-toxin was impaired in monocytes from atopic dermatitis patients." (PMID 33534121, 2021). "The expression of NLRP3 and caspase-1 was lower in atopic dermatitis skin lesions compared to those in healthy skin." (PMID 33534121, 2021). "Mast cells predominantly accumulate in the dermis of atopic-dermatitis model mice, skin-specific caspase-1 transgenic mice, as well as human atopic dermatitis patients." (PMID 30717382, 2019). "Dermatophagoides pteronyssinus, a house dust mite allergen, is an important etiology for the development of atopic dermatitis and induces assembly of the NLRP3 inflammasome complex resulting in caspase-1 activation and IL-1β and IL-18 release from keratinocytes." (PMID 33534121, 2021).
brain injury (7 papers, 2018 to 2023). Acute and chronic (see also brain INJURIES, CHRONIC) injuries to the brain, including the cerebral hemispheres, CEREBELLUM, and brain STEM. "Additionally, caspase-1-deficient mice show resistance to hypoxic-ischemic developmental brain injury." (PMID 29357878, 2018). "The highly reproducible signaling activities of caspase-1 and downstream signaling are likely indicative of a tightly regimented inflammatory response to brain trauma." (PMID 37635235, 2023). "The NLRP3 inflammasome is a key effector protein in myeloid cells such as neutrophils and monocytes that amplifies inflammatory responses and ischemic brain injury by facilitation of caspase-1 and interleukin (IL)−1 β processing." (PMID 31787973, 2019). "The immunofluorescence and Western blotting detections showed that the induction of TBI increased the expressions of NLRP3 and caspase-1 in hippocampus tissues, indicating that the activity of inflammasomes was increased by brain injuries." (PMID 30232232, 2018). "Previous studies have identified that CRID3 can inhibit ASC oligomerization in response to the stimulation of inflammasomes and further inhibit caspase-1 processing, IL-1β secretion, and pyroptosis in murine models of traumatic brain injury, dermal and pulmonary inflammation." (PMID 32861243, 2020). "Thus, of the inflammasome proteins that we tested in this study, caspase-1 and ASC are the best candidate biomarkers in serum for the care of patients with brain injury." (PMID 30596792, 2018).
cervical cancer (7 papers, 2013 to 2025). A primary or metastatic malignant neoplasm involving the cervix. "For example, elevated ROS levels in cervical cancer induce NLRP3 inflammasome assembly and caspase-1 activation, ultimately leading to pyroptosis." (PMID 41226386, 2025). "Genes PFDN4, CASP1, PLCE1, ICOSLG, GADD45G, SMARCA2, and TSPO are located in different chromosomes, and there are reports for changes in each one of these chromosomes in cervix cancer, for examples the reader is refer to:." (PMID 26388997, 2015).
co-infection (7 papers, 2012 to 2026). "In contrast, while WT mice developed larger lesions after co-infection with LCMV, lesions in caspase-1/11 deficient mice were smaller at 4 weeks post infection." (PMID 28192528, 2017). "Co-infection significantly enhanced the cleavage of caspase-1 and GSDMD in RAW264.7 cells." (PMID 41927528, 2026). "We found that, whereas a single infection with wild-type C. burnetii or with the icaA- mutants did not trigger caspase-1 activation in BMDMs, the co-infection with icaA-C." (PMID 26687278, 2015). "In addition, we also found that Asc−/− mice, caspase-1−/− mice, and Nlrp3−/− mice exhibited comparable mortality to WT controls following co-infection with P. chabaudi and C. rodentium, as did mice lacking the LPS sensors Tlr4 or caspase-11." (PMID 33440153, 2021). "The increased levels of caspase-1 and IL-1β exhibited by ART-treated HIV-infected adults with HIV viral suppression (without coinfections) may contribute to noncommunicable diseases risk among ART-treated adults with chronic immune activation among adults aging with HIV." (PMID 37953818, 2023).
dengue (7 papers, 2014 to 2025). "In dengue, primary monocytes are permissive to infection, and infection triggers late activation of caspase-1, IL-1β release and pyroptosis." (PMID 41346606, 2025). "Studies have found that dengue virus infection can induce pyroptosis of human monocytes by activating caspase-1, thus playing a role in pathogen elimination in the body." (PMID 36471417, 2022). "DENV infection activate the NLRP3 inflammasome, and subsequent activation of caspase-1, and caspase-1 dependent secretion of IL-1β in platelets microparticles from patients with dengue as well as when platelets get exposed to DENV in vitro." (PMID 33014899, 2020). "Moreover, a decrease in the expression of the inflammasome-related genes NLRP1, NLRC4, caspase-1, IL-1β and IL-18 was observed, as well as an increase in serum levels of C-reactive protein and IL-10 in dengue patients versus healthy donors." (PMID 30901375, 2019). "Dengue virus infection leads to assembly of NLRP3 inflammasomes, activation of caspase-1 and caspase-1-dependent IL-1β secretion." (PMID 25324778, 2014). "We have previously shown that during dengue there is a significant positive correlation between thrombocytopenia and IL-1β release and that dengue infection leads to assembly of NLRP3 inflammasomes, activation of caspase 1, and caspase 1–dependent IL-1β secretion in dengue." (PMID 36189282, 2022).
endometriosis (7 papers, 2021 to 2025). The growth of functional endometrial tissue in anatomic sites outside the uterine body. "Treatment with fisetin notably inhibited the NLRP3, ASC, and cleaved caspase-1 expression in endometriotic tissues of vehicle rats subjected to endometriosis." (PMID 36982152, 2023). "The latest study also demonstrated the role of NLRP3/caspase-1/IL-1β-mediated pyroptotic pathway in endometriosis." (PMID 36354688, 2022). "TRIM24 potentially facilitates endometriosis progression through the NLRP3/caspase-1/IL-1β pathway." (PMID 40508002, 2025). "Our results indicate that the exposure of MCs to estrogen stably drives NLRP3 expression critical for caspase-1 activation and IL-1β secretion, which might contribute to the local proinflammatory environment in endometriosis." (PMID 34630429, 2021). "Indeed, the NLRP3 inflammasome induces caspase-1 and IL-1β in endometriosis." (PMID 36093086, 2022).
Glucose intolerance (7 papers, 2016 to 2024). Glucose intolerance (GI) can be defined as dysglycemia that comprises both prediabetes and diabetes. "Therefore, we explored whether the changes in CNS caspase-1 activation and glucose intolerance were byproducts of diet-associated changes in the microbiome." (PMID 38840215, 2024).